KIF20A (kinesin family member 20A)
Diseases named in the same sentence as KIF20A in open-access papers (continued):
Sharing a sentence is not in itself a finding about the gene and the disease.
meningioma (2 papers, 2019 to 2022). A generally slow growing tumor attached to the dura mater. "This analysis revealed that high levels of KIFC1 (p = 0.04; HR 1.84), KIF11 (p = 0.03; HR 1.88), KIF14 (p = 0.03; HR 1.91) and KIF20A (p = 0.01; HR 2.13) were associated with a shorter progression-free survival, suggesting kinesins as novel prognostic factors in meningiomas." (PMID 30991738, 2019). "To finally address the question, if differentially expressed kinesin family members have an impact on tumor cell proliferation of meningioma cells, we performed a siRNA-mediated knockdown of KIFC1, KIF4A, KIF11, KIF14 and KIF20A." (PMID 30991738, 2019). "Therefore, we used ten meningioma tissue samples for each WHO grade and stained them for KIFC1, KIF4A, KIF11, KIF14 and KIF20A." (PMID 30991738, 2019). "Therefore, we re-analyzed our previous microarray dataset of benign, atypical, and anaplastic meningiomas (n = 62) and got evidence for differential expression of five kinesins (KIFC1, KIF4A, KIF11, KIF14 and KIF20A)." (PMID 30991738, 2019). "To query if kinesin family members might represent novel molecular therapeutic targets, we re-analyzed our previous microarray data set of benign, atypical and anaplastic meningiomas and identified five differentially expressed kinesins (KIFC1, KIF4A, KIF11, KIF14 and KIF20A)." (PMID 30991738, 2019).
microcephaly (2 papers, 2020 to 2023). A congenital or acquired developmental disorder in which the circumference of the head is smaller than normal for the person's age and sex. "According to GO analysis, these genes are associated with either abnormal hematopoiesis (Aurkb, Fen1, Hrob, Kif20a, Rad51ap1 and Tsr2) or microcephaly (Casc5, Hmgb3, Ncaph and Wdr62), or both (Fanca and Trip13)." (PMID 37661832, 2023). "Furthermore, in addition to Citron kinase and RhoA, three members of Kinesin family, Kif20a, Kif20b, and Kif4 regulate neocortical NPC cytokinesis and mutations of these genes result in reduced cortical size with microcephaly." (PMID 32159512, 2020).
Obesity (2 papers, 2022 to 2023). Accumulation of substantial excess body fat. "Several hub genes, such as TOP2A, CENPF, TYMS, AURKA, KIF4A, and KIF20A, are related to the cell cycle and DNA replication, implicating the close relationship between obesity and cancer." (PMID 36232337, 2022).
psoriasis (2 papers, 2024 to 2025). An autoimmune condition characterized by red, well-delineated plaques with silvery scales that are usually on the extensor surfaces and scalp. "Additionally, KIF4A, KIF11, and KIF20A are linked to mitotic spindle formation and chromosome segregation, processes often disrupted in hyperproliferative conditions such as psoriasis and CD." (PMID 40406126, 2025). "In psoriasis, inhibition of miR-214-3p can increase the expression of genes such as KIF20A, leading to excessive proliferation and increased apoptosis of in vitro keratinocytes." (PMID 39045407, 2024).
retinoblastoma (2 papers, 2023). A malignant tumor that originates in the nuclear layer of the retina. "Particularly, TPX2, KIF20A, CENPA, DLGAP5, and LMNB1 of HHOs were significantly enriched by the retinoblastoma (RB) immunity downregulating PD-L1 expression pathway." (PMID 37240068, 2023).
viral infection (2 papers, 2025). "These constructs were introduced into KIF20A-depleted TNBC cells via viral infection." (PMID 41392981, 2025).
and-neck malignant tumor (1 paper, 2020). "Furthermore, KIF20A-derived long peptides were identified bearing naturally processed epitopes recognized by CD4(+) T cells and CTLs, which induce tumor-specific T-helper type 1 (TH1) cells and CTLs in head-and-neck malignant tumor tissues." (PMID 32322170, 2020).
benign colorectal tumors (1 paper, 2019). "The data suggested that KIF20A was expressed at a higher level in both malignant and benign colorectal tumors than in normal tissue." (PMID 31841120, 2019).
bladder tumours (1 paper, 2019). "The in vivo experiments showed that the knockdown of KIF20A significantly inhibited the proliferation of the bladder tumours." (PMID 31093305, 2019).
cervical (1 paper, 2016). "Moreover, the KIF20A protein expression was generally negative in normal cervical tissues, weak in stage IB1 and IB2 cervical SCC tissues, and strong in stage IIA1 and IIA2 cervical SCC tissues." (PMID 27941992, 2016).
cervical tumors (1 paper, 2016). "Notably, the staining of KIF20A protein in most cancerous lesions in the primary cervical tumors was statistically higher than that in the surrounding adjacent normal cervical regions." (PMID 27941992, 2016).
Charcot-Marie-Tooth disease type 4C (1 paper, 2021). "Kinesin Family Member 20A (KIF20A) is also a protein-encoding gene, and what is known about the diseases associated with this gene is mainly familial restriction Familial Isolated Restrictive Cardiomyopathy and Charcot- Marie-Tooth Disease, Type 4C." (PMID 33912448, 2021).
colon adenocarcinoma (1 paper, 2019). "Meanwhile, data acquired from TCGA, including patients with colon adenocarcinoma and patients with rectal adenocarcinoma, were also divided into two groups according to KIF20A expression level (high and low)." (PMID 31841120, 2019).
cutaneous melanoma (1 paper, 2020). A primary melanoma arising from atypical melanocytes in the skin. "In OSskcm, KIF20A and RGS1 were found to be strongly associated with cutaneous melanoma prognosis." (PMID 32467670, 2020).
fibrosis (1 paper, 2024). the formation of excess fibrous connective tissue in an organ or tissue in a reparative or reactive process. "To date, there have been limited reports on the relationships between CCNB2, NCAPG, KIF20A, KIF11, and BUB1B with SSc or fibrosis." (PMID 38343538, 2024).
Hepatitis (1 paper, 2016). Inflammation of the liver. "Additionally, we found that the expression of Gli2, FoxM1 and KIF20A is significantly correlated with HBV-caused hepatitis, positive vascular invasion, poor histologic grade and TNM stage." (PMID 27036048, 2016).
kidney cancer (1 paper, 2023). Primary or metastatic malignant neoplasm involving the kidney. "Artificial intelligence or machine learning algorithms have been used to establish associations between KIF20A expression and survival outcomes in patients with bladder and kidney cancers." (PMID 37310408, 2023). "The future research prospects are as follows: In future studies, we should include more patients with bladder and kidney cancer in the study population and then use multiple experimental techniques to detect KIF20A expression in these patients." (PMID 37310408, 2023). "This research revealed that KIF20A was highly expressed in bladder and kidney cancers, and the higher the expression of KIF20A was, the worse the prognosis was." (PMID 37310408, 2023).
lentivirus infection (1 paper, 2019). Virus diseases caused by the Lentivirus genus. "We chose the two CRC cell lines (HCT-116 and CACO2) with the highest expression level of KIF20A and constructed shRNA-mediated KIF20A-silenced cell lines via lentivirus infection." (PMID 31841120, 2019). "Similarly, the RKO and LOVO cell lines, with the lowest expression level of KIF20A, were chosen to construct KIF20A-overexpressing cell lines via lentivirus infection." (PMID 31841120, 2019).
metastasis (1 paper, 2019). The spread or migration of cancer cells from one part of the body (where they first appeared) to another. "Additionally, lymph node metastasis and vascular invasion of the tumours were also associated with a high KIF20A expression." (PMID 31093305, 2019).
Parkinson disease (1 paper, 2025). A progressive degenerative disorder of the central nervous system characterized by loss of dopamine producing neurons in the substantia nigra and the presence of Lewy bodies in the substantia nigra and locus coeruleus. "In the KIF20A high-expression group, pathways such as cell cycle, parkinsons disease and other pathways were activated." (PMID 40822284, 2025).
prostate tumors (1 paper, 2019). "More importantly, we have demonstrated that knockdown of KIF20A can inhibit the growth of prostate tumors in vivo." (PMID 31565099, 2019).
restrictive cardiomyopathy (1 paper, 2022). A type of heart disorder referring to the inability of the ventricles to fill with blood because the myocardium (heart muscle) stiffens and looses its flexibility. "According to the literature, KIF20A plays an important role in several cardiovascular diseases, such as restrictive cardiomyopathy and acute type A aortic coarctation." (PMID 35749386, 2022).
skin basal cell carcinoma (1 paper, 2020). The most frequently seen skin cancer. "Microarray analysis based study has identified that Forkhead box M1 (FOXM1) positively regulates the expression of KIF20A and upregulation of FOXM1 is associated with several normal and transformed cells of hepatocellular and skin basal cell carcinoma." (PMID 32752229, 2020).
triple-negative breast carcinoma (1 paper, 2025). An invasive breast carcinoma which is negative for expression of estrogen receptor (ER), progesterone receptor (PR), and human epidermal growth factor receptor 2 (HER2). "KIF20A is essential for triple-negative breast cancer stem cells, and its inhibition suppresses tumor initiation and enhances chemotherapy response, offering a potential treatment strategy." (PMID 41392981, 2025).
tumor (117 papers, 2011 to 2026). "Elevated KIF20A expression has been documented in multiple cancer types and is closely associated with tumor cell proliferation, invasion, and drug resistance." (PMID 41267030, 2025). "To delineate the association between KIF20A expression and tumor immune infiltration, we performed TIMER2.0 analysis on TCGA-LUAD and LUSC cohorts." (PMID 41267030, 2025). "Consistently, re-expression of sgRNA-resistant KIF20A also rescued tumor growth defects caused by KIF20A depletion." (PMID 41392981, 2025). "Its tumor-restricted expression and association with poor prognosis position KIF20A as a potential neoantigen and therapeutic target." (PMID 41267030, 2025). "High expression of KIF20A promotes tumor proliferation, migration, and invasion and is associated with poor overall survival." (PMID 39045407, 2024). "This review focuses primarily on the expression of KIF20A in tumors, its protein structure, current developments in its inhibitors, and its application in cancer immunotherapy as a novel tumor-associated antigen (TAA)." (PMID 39272816, 2024). "Through differential gene analysis, we found that the NT5E and KIF20A genes, which are highly related to tumor development, were differentially elevated in the high-risk group." (PMID 39091494, 2024). "For instance, a microtubule-associated motor protein, kinesin-like family member 20A (KIF20A), is highly expressed in immature hematopoietic cells and functions as a prognostic factor of the tumor by correlating with Th2 and Treg cells." (PMID 38649659, 2024). "In support of this thought, further deletion of the remaining allele of the Kif20a gene in tumor cells derived from the Ptc/Kif20a double-knockout mice (cells having a genotype of Ptc−/−; Kif20afl/−) accelerated cell cycle exit." (PMID 33976373, 2021). "So far, our result suggests that samples with high KIF20A expression were likely associated with high immune infiltration in the tumour microenvironment." (PMID 33232285, 2020). "A multivariate Cox proportional hazards model showed that histologic grade, vascular invasion, Gli2, FoxM1 and KIF20A were significantly associated with tumor recurrence and overall patient survival." (PMID 27036048, 2016). "Similar trends for the cell-cycle-associated genes (ASPM, CENPE, TPX2, TRIP13, KIF11, KIF20A) were observed with their distribution in different-grade tumors, with higher expression levels observed as tumor grade increased." (PMID 23506684, 2013). "Similarly, overexpression of KIF20A is associated with increased proliferation, angiogenesis, metastasis, and drug resistance and further contributes to tumor progression and poor prognosis." (PMID 40564876, 2025). "KIF20A, which is linked to cell division, might influence the proliferation of tumor cells, thereby modulating their susceptibility to ferroptosis." (PMID 40465746, 2025). "KIF20A, a cell cycle regulator implicated in chemotherapy resistance, may influence tumor immunity, but its role in anti-PD-1 resistance remains unclear." (PMID 41267030, 2025). "Additionally, in a study that analyzed OS progression and metastasis-associated genes, KIF20A was recognized as a hub gene in OS, suggesting its important role in the progression of this type of tumor." (PMID 40427174, 2025). "This correlative finding suggests KIF20A may be associated with impaired immunotherapy response, potentially by modulating intrinsic tumor cell adaptive mechanisms." (PMID 41267030, 2025). "Overexpression of KIF20A RNA has been reported in several studies that analyzed NSCLC and SCLC tumours and is associated with poor patient prognosis; KIF20A was also identified as a component of prognostic gene expression signatures associated with drug resistance and microtubules." (PMID 40002279, 2025).
tumor (continued). "Runxiang Qiu and associates provided evidence that targeting KIF20A in medulloblastoma leads to premature cell cycle exit and enhanced neuronal differentiation, suppressing tumor growth and proposing a novel anti-proliferative treatment strategy by affecting cell fate determination." (PMID 39272816, 2024). "Additionally, it delves into the prognostic value of KIF20A across multiple cancer types, emphasizing its role as a novel tumor-associated antigen, which lays the groundwork for the development of targeted peptide vaccines." (PMID 39272816, 2024). "However, studies have shown that high KIF20A expression has been linked to reduced OS and high tumor grade, indicating a role in oncogenic processes." (PMID 36768616, 2023). "In HCC, KIF20A was also discovered to be upregulated in tumor samples, which could contribute to tumor cell proliferation and was associated with poorer tumor characteristics and shorter OS and DFS." (PMID 35123420, 2022). "Due to its interaction with immune cells (from the tumor microenvironment), KIF20A may in fact act as an underlying immunotherapy target in ccRCC." (PMID 33232285, 2020). "Moreover, KIF20A overexpression appears to be strongly associated with poor prognosis and clinical parameters of tumor patients." (PMID 33232285, 2020). "The intensity of nuclear RFP expression associated with metastasizing tumor cells, examined after 2 weeks of injection, was strongest in mice injected with HepG2/metR+shGFP cells, while it appeared much diminished in mice injected with KIF20A-depleted cells." (PMID 30813560, 2019). "Instead, our mIHC data indicate that KIF20A’s primary effect in the TME appears to be tumor cell-intrinsic, notably the significant reduction in PD-L1+ tumor cell density, rather than through direct modulation of immune cell recruitment or exclusion." (PMID 41267030, 2025). "KIF20A depletion significantly decreased tumor incidence with decreased CSC frequency for sg1 (1:574 in KIF20A-KO vs. 1:101 in control group, P = 0.000637), and a similar result was obtained for sg3 (1:277 in KIF20A-KO vs. 1:41 in control group, P = 0.00199)." (PMID 41392981, 2025). "After identifying KIF20A as the pivotal hub gene, we conducted an extensive pan-cancer analysis of KIF20A expression patterns across multiple tumor types using the TIMER2.0 platform, with a specific focus on NSCLC." (PMID 41267030, 2025). "Subsequent analysis of TCGA data via GEPIA2 revealed significantly elevated KIF20A expression in both LUAD (tumor, n = 483 and normal, n = 59, P < 0.001) and LUSC (tumor, n = 486 and normal, n = 50, P < 0.001) compared to their respective normal counterparts." (PMID 41267030, 2025). "KIF20A's prognostic importance has also been assessed in different solid tumors, where its critical function in tumour metastasis and cell proliferation has been established." (PMID 39911278, 2025). "Consistent with the TIMER2.0 results, pan-cancer analysis confirmed that KIF20A expression was markedly higher in tumor tissues than in paired normal tissues across most cancer types, particularly in NSCLC." (PMID 41267030, 2025). "To confirm this in vivo, we generated doxycycline-inducible (Dox-inducible) KIF20A or empty vector control cells and performed tumor initiation and growth assays in mice fed with Dox food." (PMID 41392981, 2025). "Given that the KIF20A inhibitor effectively targets BCSCs, while conventional chemotherapy such as carboplatin efficiently debulks the bulk tumor cells, we evaluated the therapeutic efficacy of combining carboplatin with paprotrain in vivo." (PMID 41392981, 2025). "Crucially, KIF20A-high tumors exhibited reduced PD-L1+ tumor cell density (375.4/mm2 vs. 864.8/mm2 in KIF20A-low tumors, P = 0.0002), with an inverse correlation (r=-0.249, P = 0.01)." (PMID 41267030, 2025). "KIF20A protein expression was assessed by immunohistochemistry (IHC), and tumor microenvironment (TME) profiling was performed using multiplex immunofluorescence (mIHC)." (PMID 41267030, 2025).